MIR4660 (microRNA 4660)
Synonyms: hsa-mir-4660
Gene: MicroRNA gene on chromosome 8 (9,048,445 to 9,048,518, forward strand). Ensembl gene ENSG00000263407.
Diseases named in the same sentence as MIR4660 in open-access papers:
MIR4660 is named in the same sentence as 1 disease in open-access papers, as found by Europe PMC text mining. Sharing a sentence is not in itself a finding about the gene and the disease.
MIR4660 shares sentences with these, for which no sentence is quoted: metabolic syndrome (1 paper).